F8A3 (coagulation factor VIII associated 3)
Description:
RAB5A effector molecule that is involved in vesicular trafficking of early endosomes. Mediates the recruitment of HTT by RAB5A onto early endosomes. The HTT-F8A1/F8A2/F8A3-RAB5A complex stimulates early endosomal interaction with actin filaments and inhibits interaction with microtubules, leading to the reduction of endosome motility.
Synonyms: HAP40
Tractability: Small molecule: a structure with a bound ligand is known. PROTAC: ubiquitination databases record sites on it.
Gene: Protein-coding gene on chromosome X (155,456,914 to 155,458,620, reverse strand). Ensembl gene ENSG00000277150.
Subcellular location: Cytoplasm; Nucleus; Early endosome; Nucleus, nuclear body
Gene Ontology:
Molecular function: protein binding
Biological process: negative regulation of proteasomal protein catabolic process; endosomal transport; vesicle cytoskeletal trafficking
Cellular component: cytoplasm; early endosome; nucleus; nuclear body
Homologues: Orthologues: chimpanzee F8A1 (99% identical), rat F8a1 (86% identical), mouse F8a (85% identical), tropical clawed frog f8a1 (53% identical), zebrafish f8a (51% identical), Drosophila melanogaster Hap40 (22% identical). Paralogues in human: F8A1 (100% identical), F8A2 (100% identical).
Diseases named in the same sentence as F8A3 in open-access papers:
F8A3 is named in the same sentence as 4 diseases in open-access papers, as found by Europe PMC text mining. Sharing a sentence is not in itself a finding about the gene and the disease. The quoted sentences say what the papers report.
cancer (2 papers, 2021 to 2023). A tumor composed of atypical neoplastic, often pleomorphic cells that invade other tissues. "However, despite their proximity and encoding the identical protein, F8A1, F8A2 and F8A3 each have highly distinct patterns of expression across the thousands of samples of tissues and cancers in the TCGA/GTEx dataset, indicating they may participate in different or overlapping biological scenarios." (PMID 33972602, 2021).
F8A3 also shares sentences with these, for which no sentence is quoted: autism (2 papers); neuroblastoma (1); tumor (1).